RN7SL582P (RNA, 7SL, cytoplasmic 582, pseudogene)
Gene: Miscellaneous RNA gene on chromosome 3 (116,582,552 to 116,582,830, reverse strand). Ensembl gene ENSG00000241156.
Homologues: Orthologues: chimpanzee Metazoa_SRP (98% identical), macaque Metazoa_SRP (81% identical), rabbit Metazoa_SRP (73% identical). Paralogues in human: RN7SL2 (80% identical), RN7SL1 (78% identical), RN7SL3 (78% identical), RN7SL5P (77% identical), RN7SL650P (77% identical), RN7SL357P (76% identical), RN7SL126P (76% identical), RN7SL4P (76% identical), RN7SL732P (76% identical), RN7SL321P (75% identical), RN7SL480P (75% identical), RN7SL118P (75% identical), and 700 more.